HES1 (hes family bHLH transcription factor 1)
Diseases named in the same sentence as HES1 in open-access papers (continued):
Sharing a sentence is not in itself a finding about the gene and the disease.
cancer (continued). "Quantitative RT–PCR analysis was used to verify that SOX1 controlled the expression of genes related to pathways in cancer, such as LAMB3, FN1, and HES1, and the focal adhesion pathway, including LAMB3 and FN1." (PMID 37190139, 2023). "HES1 has also been reported to promote EMT, contribute to metastasis and contribute to increased multidrug resistance of cancer cells." (PMID 36831452, 2023). "For example, burden tests within specific cancer types have identified NCVs in the promoters of TERT, FOXA1, HES1, SDHD, and PLEKHS120–22." (PMID 36808133, 2023). "Consistent with elevated JAG1 in ICC/IDC cancer cells, NOTCH target genes were significantly increased in endothelial cells in clusters 0 (HES1) and 22 (HES1 and HEY1) and SMC (HES4) located the ICC/IDC TME compared to benign prostate." (PMID 36229464, 2022). "Accordingly, IFN-I exposure induced significant upregulation of Klf4, Oct3/4, Sox2, Nanog, hes family bHLH transcription factor 1 (Hes1) and Nes, and endowed MCA205 and AT3 cancer cells with increased sphere-forming ability." (PMID 36002648, 2022). "ZEB1, HES1, NR6A1, PATZ1, PAX4 and MTF1—have a reported oncogenic role in cancer types other than HCC." (PMID 33541355, 2021). "CD4+CD45RO+ T cells in the lesional blood highly expressed genes relating to cancer progression and CTCL pathogenesis: RGS1, RDH10, HES1, DNAH9, ANK2, and SGK1 16–25." (PMID 34608214, 2021). "A. Distribution and alteration frequency of Hes1, Hey1, Notch1, Notch2 and Notch3 in breast, ovarian, bladder, head and neck (HNCC) and clear cell renal cell carcinoma (ccRCC) cancer types." (PMID 31470883, 2019). "During the process of dedifferentiation, multiple genes that were demonstrated to be pivotal in cancer stem cell properties were induced, including PDGFRB, NOTCH1, JAG1, HES1, and HEY1 of the Notch signaling, SNAI1 and SNAI217–20." (PMID 29991717, 2018). "Both Hes1 mRNA and protein levels were significantly reduced in CCR7-null cancer stem cell-like populations, either sorted for CD24+CD29hi expression by FACS or selected through culturing as secondary mammospheres." (PMID 28137279, 2017). "Inhibition of Notch1 reduces cancer stem cell function, reduces expression of Notch target genes HES1, HES5 and HEY-L, and reduces the population of CD44HiCD24low, a population identified as cancer stem cells." (PMID 28594912, 2017). "The qRT-PCR analysis of Hairy and Enhancer of Split 1 (HES1), that functions in the maintenance of cancer stem cells, showed a significant increase after seven days of treatment with afatinib alone or in combination with TPCA-1 in PC9 cells." (PMID 28521301, 2017). "Second, suppression of PTEN expression by shRNA in Hes1-repressed CNE2 cells rescued PI3K/AKT activities and the migration/invasion of cancer cells." (PMID 26452025, 2015). "Compared with that in normal urothelium cells and other cancer cells, the RNA expression of HES1 and HES4, effectors of Notch signalling, at the single‐cell level is significantly lower in TPCS." (PMID 39731353, 2025). "Notably, ERE was identified in the promoter of HES1 gene and both ESR1 and ESR2 were found to control HES1 expression in human cancer cells." (PMID 40506655, 2025). "Interaction between HES1, a downstream effector of Notch, and PARP-1 has been identified to finally induce apoptosis in B leukemic cells, as a protective mechanism against this type of cancer." (PMID 39858519, 2025). "Furthermore, we also observed the downregulation of the mRNA expression of several key cancer stemness markers following CLF treatment, including CD44, CD24, BMI1, and HES1." (PMID 41303378, 2025). "Non-NE cancer cells exhibited higher Notch signaling activity (i.e., high HES1 and NOTCH1/2 expression) and higher nuclear AR levels." (PMID 39024561, 2024). "On the other hand, tumor necrosis factor alpha was shown to increase the content of cancer stem cells in oral squamous cell carcinoma by activating Notch-Hes1." (PMID 37219449, 2023).
cancer (continued). "A handful of Notch direct target genes have been reported, including HES1, HEY1, p21, c-Myc, and Slug, whose dysregulation is frequent in cancer." (PMID 36438567, 2022). "Among them, several genes that promote tumorigenesis in cancer cells, including STAT3, HES1, and genes related to NF-κB signaling could be targeted by miR-23a and miR-146b." (PMID 34316033, 2022). "Furthermore, HES1 functioned as an important contributor to regulate BCSC stemness and cancer cell proliferation in TNBC through elevating Slug expression, both in vitro and in vivo." (PMID 33390847, 2021). "To explore whether HES1 is a functional gene in BCSCs and how HES1 maintains stemness of BCSCs in TNBC, we investigated cancer stemness properties by a series of assays and their corresponding rescue assays." (PMID 33390847, 2021). "EGR2 induces apoptosis in several cancer cell lines, ETV3 contributes to growth arrest, HES1 is involved in DNA interstrand crosslink damage repair and could participate in response to DNA adducts induced by DEN." (PMID 34383828, 2021). "Additionally, we observed that METTL3 is involved in the modulation of Notch signaling pathway (including METTL3 DLL3, HES1, and NOTCH3 genes) (q-value < 0.05), which plays an important role in tumorigenesis and cancer development." (PMID 34589481, 2021). "Meanwhile, HES1 knockdown reduces BCSC self-renewal, BCSC population, and cancer cell proliferation in TNBC, whereas overexpression of Slug restores the oncogenic function of HES1, both in vitro and in vivo, suggesting that HES1 performs its oncogenic role through upregulating Slug." (PMID 33390847, 2021). "MDK-induced NF-κB also increased cancer cell proliferation through PI3K-Akt signaling and Hes1 triggered epithelial-to-mesenchymal transition via increased Vimentin and Snail levels, and decreased E-cadherin levels, which were not recovered by survivin expression under MDK knock down and hypoxia." (PMID 32847073, 2020). "In contrast, proteins that promote various cancer malignant properties, including CCND1, ERBB2, SNAIL, SLUG, phosphorylated STAT3 (p-STAT3), FAK, FOXM1, ETS1, YAP, HES1, and OCT4, were all significantly downregulated, an indication of reduction of malignancy in the cancer cells after EZH2 knockdown." (PMID 31130994, 2019). "Recently, it has been shown that an antibody against the negative regulatory region (NRR) of Notch1 resulted in reduced proliferation, restricted expression of its targets HES1, HES5, and HEY-L, reduced colony forming ability, and lessened cancer stem-like population in MDA-MB-231 cell lines." (PMID 31379945, 2019). "This pathway could participate in the phenotype reprogramming observed in Caco-2/HT29MTX co-cultures treated with oleic acid through transcriptional induction of HES1, since this gene is inducible by AMPK in cancer cells." (PMID 28726765, 2017). "The uncovered regulation between RET, miR-182 and HES1 clearly points toward new prognostic and therapeutic options by using components of the RET-NF-κB/miR-182-HES1/Notch1 axis as potential key targets to restrict cancer progression." (PMID 28122586, 2017). "Overexpression of the transcriptional factor Hes1 (hairy and enhancer of split-1) has been observed in numerous cancers, but the precise roles of Hes1 in epithelial-mesenchymal transition (EMT), cancer invasion and metastasis remain unknown." (PMID 26452025, 2015). "Hes1 binds to the Bmi-1 locus and upregulates Bmi-1expression, which consequently downregulates PTEN and activates the Akt/GSK3β pathway, induces EMT and cytoskeleton reconstruction, ultimately leads to enhanced invasiveness of cancer cells." (PMID 26452029, 2015). "HES1, CTAG2 and KLF10 have all been shown to play a role in cancer biology." (PMID 24885297, 2014). "Hes-6 has been described as an inhibitor of Hes-1 during neuronal development, although its function in cancer is not known." (PMID 19891787, 2009).
cancer (continued). "Moreover, several studies revealed a negative correlation between HES1 expression and the survival of metastatic patients of different cancers, producing drug resistance by maintaining cancer cells in a quiescent state." (PMID 39400678, 2025). "With respect to insight into anti‐cancer signaling of CaNV+MB‐Drug, the expression of Notch‐1 downstream factors (cleaved Noth‐1 and HES‐1) significantly increased, while Notch‐1 expression remained unchanged, indicating Notch‐1 pathway as a major mechanism to drive the CaNV+MB‐Drug effect." (PMID 34664430, 2021). "Hence, the current study set out to examine whether miR-216b inhibits cancer growth in OS by reducing the levels of JMJD2C and HES1." (PMID 32972441, 2020). "However, the complex regulatory machineries of Hes1 during cancer stem cell induction and metastasis promotion have not been fully elucidated." (PMID 26452029, 2015). "In addition, the localization of Hes1 was found in both the nucleus and cytoplasm of NP69, CNE2, and SUNE1 cells, based on immunofluorescence assay, and the distribution of Hes1 was detected in the nucleus and cytoplasm of cancer cells based on IHC." (PMID 26452025, 2015). "Therefore, Hes1 may be a promising therapeutic target for the treatment of advanced NPC by inhibiting EMT, invasion and metastasis of cancer cells." (PMID 26452025, 2015). "One study regarding the integrative genomic analyses of the HES/HEY family presumed that Notch-independent HES1 and 3 transcription occurred in undifferentiated ES cells, and that Notch-dependent HES1 and 5, HEY1 and 2, and HEYL transcription occurred in fetal, adult or cancer tissue." (PMID 23420695, 2013). "Chrysin-treated anaplastic thyroid cancer (ATC) tumors revealed increased protein levels of Notch1 and Hes1 (hairy/enhancer of split 1), and activated Notch1 might induce cleaved Poly ADP ribose polymerase (PARP) protein, indicating that apoptosis could be induced to inhibit cancer cells." (PMID 36678588, 2023). "Furthermore, we indicated that Bmi-1 mediated Hes1-induced cell proliferation and migration, downregulated PTEN and activated the Akt/GSK3β pathway, consequently induced EMT and cytoskeleton reconstruction, ultimately leading to enhanced invasiveness of cancer cells." (PMID 26452029, 2015). "ASCL1 KO tumors developed a poorly differentiated carcinoma without detectable expression of the NE lineage markers SYP, INSM1, or DLL3 but showed higher expression of NOTCH2, HES1, and KRT8." (PMID 39024561, 2024). "In this study, DAPT inhibited cancer growth both in vitro and in vivo, but Notch2/DLL rather than Notch1/Hes1 signaling was responsible for those effects in GH3 cells." (PMID 31508369, 2019). "We further detected the expression of some reported stemness-related genes in HCC and CRC stem cells including CTNNB1, HES1, SMAD4, GLI1, STAT3 and BMI122, 23, 24, 25 in the cancer cell lines with or without PS341 treatment." (PMID 26915315, 2016).
infection (14 papers, 2011 to 2025). The state of being infected such as from the introduction of a foreign agent such as serum, vaccine, antigenic substance or organism. "The use of 25 to 100 mg/kg of baicalin upregulated Notch 1, RBP-J, JAG1, and HES1 mRNA expression levels from the blood vessels compared to the infection group (p < 0.01)." (PMID 40427615, 2025). "In contrast, recruitment of EBNA2 to host genes IL7 and HES1 was more efficient after the LPKOw infection, consistently showing elevated EBNA2 binding on days 2 and 5, but not at later time points." (PMID 29462212, 2018). "In TNwt- and TNrvIE1-infected NPCs, protein levels of Hes1 were downregulated to 32.5±0.04% and 32.0±0.08% of that in mock-infection, respectively." (PMID 28750047, 2017). "The knocking down of SRCAP could block TA-12 infection, downregulate HES1 and upregulate RBP-Jκ, which was consistent with those of the LY-411575, an inhibitor of Notch signaling." (PMID 39530666, 2024). "Levels of Hes-1 were significantly increased on day 14 and 21 post-infection (pi)." (PMID 21155842, 2011). "In contrast, WT infection induced significantly higher expressions of genes that negatively regulate type I IFN expression, such as AHR, DUSP1, HES1, and PRDM1, compared to the mutant-infected cells." (PMID 37513744, 2023). "Instead, four IFN expression inhibitory genes (AHR, DUSP1, HES1, and PRDM1) were significantly up-regulated by WT infection." (PMID 37513744, 2023). "We found that induction of HES1 and OLFM4 and the down-regulation of ATOH1 transcript levels was consistent with the increased Notch-1 signalling in crypts at the peak of infection." (PMID 28323899, 2017). "At 8 days post infection with NICD-Ad, we observed enhanced Hes1 mRNA expression in both total BMSCs and c-KitPOS/NKX2.5POS BMSCs, compared with expression in controls (NC-Ad and MOCK)." (PMID 25956503, 2015). "The mRNA expression of Notch1, DLL1 and Hes1 were significantly higher in patients with moderate/severe TB compared to those with mild TB or no infection." (PMID 37063841, 2023). "Infection with Ad-CMV-Cre resulted in the deletion of Rbpj and the loss of the stimulatory effect of the NOTCH2 gain-of-function on the Notch target genes Hes1, Hey1, and Hey2 (not shown) since RBPJκ is required for their induction by Notch." (PMID 37865314, 2023). "At 2 days after infection, EBV markedly induced expression of MYC, CD21, CD23, HES1, and BATF (positive controls) 10- to 20-fold, possibly through EBNA2; in contrast, host housekeeping genes including β-2 microglobulin (B2M) and RNA polymerase II (POLR2A) were unaffected." (PMID 30487153, 2018). "The fact that Hes1 downregulation occurs as early as 12hpi and the requirement for de novo viral protein synthesis suggest the potential involvement of HCMV proteins present during the IE phase of infection." (PMID 28750047, 2017). "In addition, Hes1 level was increased in H9c2 cells treated by LV-N1ICD infection and H/R, but decreased in H9c2 cells treated by LV-N1ICD-shRNA infection and IPC or IPost, confirming that Hes1 is a target gene of Notch signaling." (PMID 24098939, 2013). "Notably, the protein level of Hes1 was minimally affected by IE2 in the absence of IE1 during the IE phase of infection." (PMID 28750047, 2017). "We found three genes that were commonly activated with infection with SCV2 at both 12 and 24 hpi (DUSP1, HES1, KLF2) and some non-congruent genes at 12 hpi (CCL5, ZBP1, NRXN2, STAB1, SLC25A47, CXCL11) and 24 hpi (FOXA2, RHOB)." (PMID 37504520, 2023). "Two days post infection, known EBNA2-induced genes CD21 and HES1 were not induced by E2KO, but were induced normally by the EBNA-LP mutants, suggesting that EBNA-LP does not enhance the transcription of these genes by EBNA2 in the context of EBV infection." (PMID 29462212, 2018).
infection (continued). "Ad-CMV-Cre, but not Ad-CMV-GFP, infection led to the inversion of the conditional by inversion (COIN) module and expression of the Notch2ΔPEST or Notch2ΔINV mRNA with the consequent induction of Hes1, Hey1, and Hey2 demonstrating activation of Notch signaling." (PMID 37865314, 2023). "We have previously shown that Jag1 and NICD1 protein levels did not decrease before 16-24hpi, which was after Hes1 downregulation started (12hpi), indicating the Hes1 downregulation is not a consequence of Jag1 and NICD1 dysregulation in the IE phase of infection." (PMID 28750047, 2017).
cardiovascular disease (3 papers, 2021 to 2025). "Laboratory evidence indicates that among the Notch receptors, Notch1/Hes1 signaling modulates not only cell proliferation but also apoptosis in the initiation and progression of tumors and cardiovascular diseases." (PMID 38703204, 2024). "In cardiovascular disease, celecoxib may be by Notch1/Hes1 signaling pathway to protect the heart from hypertrophy and inflammation." (PMID 40271123, 2025).
neurodegenerative disease (3 papers, 2006 to 2022). A disorder of the central nervous system characterized by gradual and progressive loss of neural tissue and neurologic function. "Furthermore, low-molecular compounds, such as Hes1 dimer inhibitors for neural stem cell (NSC) differentiation and histone deacetylase 3 (HDAC3) inhibitors and SIRT2 inhibitors for neurodegenerative diseases, can be used in combination with immunotherapy." (PMID 35214143, 2022).
Heart Disease (2 papers, 2009 to 2021). "Although Hes1 has not been previously implicated in heart development, mice lacking Hes1 display arterial pole alignment anomalies, including overriding aorta and ventricular septal defects, common components of congenital heart disease in man." (PMID 19609448, 2009).
hematological malignancies (2 papers, 2022 to 2025). "Recently, it was shown that the Fanconi anemia protein FANCD2 and Hairy Enhancer Split 1 (HES1) collaborate in the transcriptional repression of PPARγ to keep hematopoietic stem cells in a quiescent state and to avoid stem cell exhaustion, as well as hematological malignancies." (PMID 35954274, 2022).
bone disorder (1 paper, 2024). "The mechanisms through which the AhR and Hes1 are regulated must be explored further to better understand CKD-related bone disorders." (PMID 39201457, 2024).
gynecologic tumors (1 paper, 2025). "Notably, reduced DLL1 and HES1 expression was also detected in HGSOC when compared to other (non-type II) gynecologic tumors (FC = 1.17 and 1.43, respectively; p < 0.02)." (PMID 40002854, 2025).
metabolic disease (1 paper, 2024). A congenital disorder (due to inherited enzyme abnormality) or acquired (due to failure of a metabolically important organ) disorder resulting from an abnormal metabolic process. "HES1, for example, is involved in the regulation of developmental processes and cell differentiation, and its association with metabolic diseases suggests a potential role in the regulation of pancreatic β-cell function and insulin secretion." (PMID 39926598, 2024). "Other hub RMITRGs, such as HES1, TMBIM6, TSPAN13, and VMP1, also showed significant associations with metabolic diseases, highlighting the diverse molecular pathways involved in T2D." (PMID 39926598, 2024).
neurological disorders (1 paper, 2019). "Together, our results indicated that Hes1 expressed in both excitatory and inhibitory neurons plays an important role in the adult brain functions and suggested that two types of Hes1 cKO mice described here might be useful for analyzing various neurological disorders." (PMID 31160641, 2019).
HES1 also shares sentences with these, for which no sentence is quoted: adenocarcinoma (3 papers); depression (2); Hepatic steatosis (2); ischemic cardiomyopathies (2); lung disease (2); meningioma (2); Myocardial fibrosis (2); Obesity (2); ovarian tumors (2); type 2 diabetes (2); Adams-Oliver syndrome (1); anaplastic astrocytoma (1); Azoospermia (1); B-cell acute lymphoblastic leukemia (1); basal cell carcinoma (1); benign gynecologic tumors (1); bipolar disorder (1); bone tumor (1); brain tumor (1); breast (1); carcinoid tumor (1); cholesteatoma (1); chronic rhinosinusitis (1); clear cell renal cell carcinoma (1); cleft palate (1); corticotropinomas (1); Cyclic neutropenia (1); cyst (1); dementia (1); Down syndrome (1).
A further 59 diseases each share a sentence with HES1 in 1 paper.